BCL2 (BCL2 apoptosis regulator)
Diseases named in the same sentence as BCL2 in open-access papers (continued):
Sharing a sentence is not in itself a finding about the gene and the disease.
tumor (continued). "Using Lewis lung cancer mice model, intraperitoneal injection of Tan IIA at 15 mg/kg significantly inhibited tumor growth, neovascularization, and Bcl-2 expression and increased the levels of CD4+, CD4+/CD8+, and NK cells." (PMID 32265690, 2020). "The nanopolyplexes mediated intracellular restoration of tumor suppressor miR34a was evaluated by using Western blotting to quantify the expression level of the Bcl-2 protein." (PMID 33255217, 2020). "In this study, we detected that mitochondrial morphological changes in tumor tissues of NPC patients infected with EBV were accompanied by an elevated expression of BHRF1, an EBV encoded protein homologue to Bcl-2." (PMID 32392902, 2020). "Further, decreased levels of the anti-apoptosis protein Bcl-2 were observed in lung lysates from mice treated with Dox-fReANCs compared to untreated mice and non-tumor-bearing mice." (PMID 33134314, 2020). "At protein level, we analyzed PCNA and BCL2 as protein markers for tumour proliferation and anti-apoptosis, respectively." (PMID 32251338, 2020). "Further, the combination of GS and DOX also inhibited tumor growth in BALB/c mice model by suppressing the expression of Bcl-2 and P-gp." (PMID 36046484, 2020). "To elucidate the possible mechanism of GQN in the antitumor effect, we measured the gene transcription of Bax, Bcl-2, and Caspase 3, which are associated with apoptosis, and VEGF, a signaling factor for angiogenesis in tumor tissues." (PMID 32831873, 2020). "ERK1/2 promotes cell survival in BRAF- or KRAS-mutant tumor cells by increasing the expression of pro-survival BCL-2 proteins and further stabilizes the MCL-1 protein." (PMID 33308268, 2020). "STAT3 is an important member of the STATs family and can regulate a variety of key tumor factors, including the anti-apoptotic gene BCL-2 and the cell cycle control gene c-MYC." (PMID 33746736, 2020). "Meanwhile, p-Akt was reported to inhibit Bax and activate caspase, which can enhance the activity of NF-κB while increasing Bcl-2; as such, the endogenous apoptotic pathway was blocked to abolish the apoptosis of tumor cells." (PMID 32049100, 2020). "In contrast to hematologic malignancies, where BCL-2 seems most important for tumor cell survival, the response of solid tumors to antiapoptotic BCL-2 protein inhibition is far more complex, due to their heterogeneity." (PMID 33070156, 2020). "It is known that the pro-inflammatory transcription factor NF-κB promotes and stimulates the expression of anti-apoptotic biomarkers (tumor-promoting proteins) such as survivin, Bcl-2, and Bcl-xL." (PMID 32708030, 2020). "Overexpression of CD59 can increase the expression of anti-apoptotic protein Bcl-2 and promote tumor cell growth and proliferation." (PMID 31413735, 2019). "Increasing tumour suppressor of microRNA expression sensitised both drug resistant and parental cell lines to chemotherapeutic agents, in part through targeting of BCL2." (PMID 35582270, 2019). "Xenograft tumor tissues were used to investigate the effect of Dis on apoptosis markers, Bax and Bcl-2." (PMID 31295840, 2019). "Here, we disclose a bottlebrush-architectured poly(ethylene glycol) (PEG)–siRNA conjugate as an in vivo vector to suppress the antiapoptotic B cell lymphoma 2 (Bcl-2) family proteins in a tumor xenograft mouse model." (PMID 30801019, 2019). "Imbalance of the Bax/Bcl-2 ratio can change tumor cells sensitivity to cell death induced by chemotherapeutic drugs or radiation." (PMID 31013662, 2019). "Increase in expression of Bcl-2 in transgenic models will result in evasion of normal cell death mechanisms leading to accumulation of cells and tumor formation." (PMID 31288815, 2019).
tumor (continued). "Q-PCR analysis indicated that costunolide upregulated the expression of puma and Bax mRNA and downregulated the expression of Bcl-2 mRNA in xenografted tumor." (PMID 31242894, 2019). "Therfore, it seems that Bcl-2 inhibitors are able to sensitize tumor cells to conventional chemotherapeutic agents and reverse the resistance caused by the disregulation of the apoptotic machinery." (PMID 31664947, 2019). "Mice receiving pacRNAClv showed the most appreciable down-regulation of Bcl-2 protein expression (62% knockdown) following treatment, as evidenced by Western blotting of homogenized tumor tissues." (PMID 30801019, 2019). "We observed a similar anti-correlation of MYC and BCL2 protein levels in immunohistochemical (IHC) stainings of human SCLC tumor specimens (n = 48)." (PMID 31375684, 2019). "In this study, we investigated the anti-tumorigenesis effects of Dis, and findings showed that Dis inhibits tumor growth rate through induction of apoptosis in nude mice via overexpression of Bax and inhibition of Bcl-2." (PMID 31295840, 2019). "IL-24 can also downregulate anti-apoptotic proteins such as Bcl-2 and Bcl-xL and produce of tumor-suppressing ceramides leading to endoplasmic reticulum stress, autophagy, and apoptosis in PCa." (PMID 30669553, 2019). "Inhibiting apoptosis by upregulating BCL2 transcription, increases BCL2 activity and results in progressive tumor growth." (PMID 31648231, 2019). "A subclonal NRAS G13A mutation (VAF 0.03) was detected in the oligoclonal tumor arising from MYC, BCL2, P53dd transduced cells." (PMID 31586074, 2019). "Data obtained from murine cancer models supports a mechanistic role for RAGE activation whereby induction of cell signaling proteins such as AKT proteins, the anti-apoptotic protein, BCL2, and cyclin D1, promote tumor cell proliferation." (PMID 31665084, 2019). "Lastly, a study with an HCC rat model showed that probiotic fermented milk and chlorophyllin slow down tumor growth and volume for 40%, by reducing expressions of c-myc, bcl-2, cyclin D1, and rasp-21." (PMID 30658519, 2019). "After treatment with COS, significantly elevated concentrations of Bax and reduced expression of Bcl-2 in tumor tissues, as well as elevated levels of TNF-α, IL-2, Fas and Fas-L in mice serum were observed (p < 0.05)." (PMID 30791594, 2019). "Costunolide upregulated the expression of puma and Bax mRNA and decreased the expression of Bcl-2 mRNA in xenografted tumor." (PMID 31242894, 2019). "Overall, this study demonstrates that targeting antiapoptotic BCL2 protein signaling in combination with AR inhibition results in enhanced tumor cell killing, suggesting this is a promising therapeutic strategy with the potential for clinical development." (PMID 31228231, 2019). "For example, berberine can upregulate the expression of the pro-apoptotic protein BAD in HL-60 cells and downregulate the expression of anti-apoptotic protein Bcl-2 to achieve regulation of tumor cell apoptosis." (PMID 30837865, 2019). "Both of these studies have suggested that miR-16 exerts its tumor suppressor effect by post-transcriptionally targeting the anti-apoptotic gene BCL2 resulting in apoptosis of the tumor cells." (PMID 31648231, 2019). "Hsa_circ_006100 was found to positively regulate PCNA and BCL‐2 levels in the tumour tissues via miR‐195." (PMID 31318114, 2019). "Immunohistochemical analysis revealed tumor cells were positivity for Bcl2, CD5, and p40, while infiltrated lymphocytes were positive for CD3 and negative for CD99." (PMID 31655916, 2019). "Consistently, IHC showed Bcl2 staining was also strengthened when PVT1 was overexpressed in the orthotopic GC tumor." (PMID 31205469, 2019).
tumor (continued). "(1→3)-β-d-glucan increased the ratio of Bax to Bcl-2 at the translational level by up-regulating Bax expression and down-regulating Bcl-2 expression, resulting in the initiation of apoptosis of S180 tumor cells." (PMID 31877995, 2019). "BCL2, c-FOS and HIF1a are transcription factors, whose dysregulation were broadly reported to be associated with tumor inflammation, angiogenesis, and suppression of apoptosis among others." (PMID 31754348, 2019). "Data of animal study showed that Dis reduces the tumor growth rate and tumor weight significantly in dose-dependent manner, however protein expression changes of Bax and Bcl-2 significantly observed only in high dose of Dis treated mice." (PMID 31295840, 2019). "The disregulation of Bcl-2, an anti-apoptotic protein, is crucial for the tumoral development and chemoresistance." (PMID 31664947, 2019). "MiR-16 is characterized as tumor-suppressive miRNA, exerting its function by targeting the Bcl-2-regulated apoptotic pathway." (PMID 31443224, 2019). "Firstly, we investigated the genes, encoding globular Bcl-2 members and their putative BH3-like interactors, characterized by changes in expression levels between tumor and tumor-adjacent normal tissues." (PMID 31825969, 2019). "Immunohistochemically tumor cells were positive for Bcl2 and Cytokeratin AE1 + AE3, while infiltrated lymphocytes were positive for CD3 and CD5 and negative for CD99." (PMID 31655916, 2019). "Blocking or down-regulating the expression of Bcl-2 can promote the apoptosis of tumor cells and enhance the sensitivity of tumor cells to radiotherapy and chemotherapy, so as to improve the therapeutic effect of tumors." (PMID 31072916, 2019). "Bax is a pro-apoptotic protein, whereas Bcl-2 is an anti-apoptotic protein and immunostaining for these proteins indicate that they were present in the cytoplasm of tumor cells." (PMID 30578377, 2019). "BCL2 is typically used as a clinical marker for tumor detection, and its downregulation confirms that tumor cell growth is significantly inhibited." (PMID 31534470, 2019). "The results showed significantly decreased expression of p-STAT3 and Bcl-2 in the combination therapy group (**P<0.01) E. Representative image of TUNEL assay in tumor tissue." (PMID 31777595, 2019). "Significant induced tumor suppression and reduced expression of Bcl-2 had been observed after AdCN205-IL-24-miR-34a infection in comparison with AdCN205-IL-24 or AdCN205-miR-34a alone in vitro and vivo." (PMID 31781493, 2019). "With regard to a targeted induction of apoptosis, a direct coupling of Bcl-2 antagonists to tumor specific antibodies or a combination of Bcl-2 antagonists with immunotoxins represent promising, new therapeutic approaches." (PMID 31312616, 2019). "The IL-6/STAT3 pathway regulates a number of gene expressions such as Bcl-2 that mediate proliferation or inhibit apoptosis during tumor formation." (PMID 31361777, 2019). "In all, Galectin-3 and Galectin-1 support high fidelity and prolonged Ras signaling downstream to Raf or PI3-kinase, and they also control Ras-regulated tumor suppressor, e.g., Bcl2 or β-catenin, thereby supporting tumor survival." (PMID 31861875, 2019). "Overexpression of antiapoptotic molecules, such as Bcl-xL or Bcl-2, promoted lymphocytes survival as well as improved anti-tumor efficacy." (PMID 31398192, 2019). "It is well established that Bcl-2 facilitates cell survival, playing an important role in tumor initiation and maintenance." (PMID 31655833, 2019). "Overexpression of Gm40600 suppressed SP 2/0 cell proliferation and isograft tumor growth by reducing Blimp1 and Xbp1-mediated transcription of the anti-apoptosis molecule Bcl2." (PMID 31311517, 2019). "The serine/threonine kinase Akt has long been known for its role in cell survival and proliferation via modulation of its downstream substrates such as glycogen synthase kinase-3 (GSK3), FoxO, Bad and Bcl2, etc. in promoting tumor growth." (PMID 31360736, 2019).
tumor (continued). "Conversely, miR-34a experimental induction exerts tumor suppressive effects in CSCs by inhibiting BCL2 Apoptosis Regulator (BCL2) and NOTCH1/NOTCH2 genes and boosting DNA damage responses." (PMID 31450858, 2019). "High NCL and Bcl‐2 expression in tumor cells, along with their involvement in cell apoptosis, suggests that they play a relevant role in tumor cell drug resistance." (PMID 31127617, 2019). "In conclusion, downregulation of Bcl-2 induced by miRNA-34a can overcome tumor cell resistance to IL-24 and enhanced its anti-tumor effect." (PMID 31781493, 2019). "Results manifested that compared with those in para‐carcinoma tissues, Ezrin, LaminA/C, and cleaved caspase‐3 expressions were significantly declined in tumor tissues (P < 0.01), but the Bcl‐2/Bax ratio was increased significantly (P < 0.01)." (PMID 31578772, 2019). "In Phase 1 studies in patients with relapsed or refractory CD20+ lymphoid malignancies, the Bcl2 inhibitor navitoclax combined with rituximab displayed essential clinically activity by safety, pharmacokinetics, and anti-tumor activity analyses." (PMID 31534865, 2019). "Of note, the incorporation of the antipoptotic Bcl-2 conversion gene in the systems resulted in an effective inhibition of tumor growth after 7 days in vivo when injecting into a solid tumor of nude mice." (PMID 30960498, 2019). "We also examined the expression levels of Caspase-3 and Bcl-2 in tumor tissues harvested from these mice by using immunohistochemistry analyses." (PMID 31695794, 2019). "We found that BCL-2 level in ECPU-0001 treated group’s tumor was significantly (p < 0.05) reduced compared to control group." (PMID 31450709, 2019). "RT-qPCR analysis revealed that, compared with the sh-NC group, the mRNA expression level of LC3B and BAX mRNA was increased in the sh-CASC9 tumor tissues, whereas the mRNA expression level of P62 and BCL-2 was decreased (P < 0.05)." (PMID 30674868, 2019). "C. Typical image of immunohistochemistry (IHC) staining of P-STAT3 and Bcl-2 in tumor tissues (×200)." (PMID 31777595, 2019). "In fact, there is growing interest in targeting Beclin-1/Bcl-2 interaction for identification of autophagy and apoptosis activators for reducing tumor growth." (PMID 31527516, 2019). "Overexpression of Bcl-2 in tumours can sensitise them to apoptosis when the function of Bcl-2 is inhibited, and in some cancers, high Bcl-2 expression is associated with better prognosis." (PMID 31681471, 2019). "Using the Systemsdock platform for molecular docking analysis, we observed that ALO expectedly docked into the active pocket of the Bcl2 structure, suggesting that Bcl2 is a direct target through which ALO exerts its anti-tumor activities." (PMID 31534865, 2019). "The strategy consisted in addressing the tumor trough PSMA, a protein overexpressed in the surface of prostate cancer cells and tumor vascular endothelium, with a PSMA aptamer linked to PLK-1 and BCL-2 siRNAs." (PMID 31888119, 2019). "At the same time, BCL2 is advantageous for promoting tumor cell survival, which is consistent with the effectiveness of BCL2 inhibition in BPDCN32,33." (PMID 31811114, 2019). "The resistance to cell death, occurring upon disturbed balance of the Bax/Bcl-2 ratio, can be related to tumor cell invasion, cell metastatic." (PMID 31340610, 2019). "Further characterization of tumor features that modulate BCL-2 dependency is however required to clearly define the clinical utility of these BH3 mimetics." (PMID 30631150, 2019).
tumor (continued). "Gm40600 reduced SP 2/0 cell proliferation and isograft tumor growth and progression by suppressing Blimp1 and Xbp1-mediated Bcl2 transcription to induce apoptosis." (PMID 31311517, 2019). "Similar to an apple that seems healthy but is poisoned, BH3 mimics the ‘poisonous’ BCL-2 by blocking its protective function by directly binding to its BH3 domain, favoring the death of tumor cells that depend on the increased production of BCL-2." (PMID 31827894, 2019). "Expression differences in the pro-apoptotic Bcl-2 members and the mitochondrial priming state of tumor cells is an important indicator of chemotherapeutic response." (PMID 30774992, 2019). "Overexpression of anti-apoptotic BCL2 proteins such as BCL2, BCL2L1 and MCL1 is widely associated with tumour initiation, progression and chemo resistance in AML." (PMID 31018543, 2019). "This phosphorylation prevents the binding of BTB–CUL3–RBX1 (BCR) E3 ligase to Bcl-2, thereby inhibiting the degradation of Bcl-2 and inhibiting the apoptosis of tumor cells." (PMID 31921178, 2019). "The heterogenous pattern of BCL2 expression in FL mirrors the variable presence and types of BCL2 gene abnormalities in tumor cells." (PMID 30931307, 2019). "The combination treatment upregulated more significantly the protein expression of cleaved caspases 3 and cleaved PARP and suppressed the Bcl-2 expression level in tumor samples, compared to each single treatment with paclitaxel or XAV939." (PMID 31416135, 2019). "This is also in agreement with previous study suggested that BCL2 inhibition suppressed tumor growth in NB." (PMID 31889909, 2019). "WB analysis showed that costunolide increased the expression of cleaved caspase 9, cleaved caspase 3 and Bax proteins and decreased the expression of Bcl-2 protein in xenografted tumor." (PMID 31242894, 2019). "Immunohistostaining of tumor sections using anti–Bcl-2 antibodies revealed substantially reduced Bcl-2 immunoreactivity (brown deposits) in pacRNAClv-treated tumors compared with pacRNANClv- and vehicle-treated groups." (PMID 30801019, 2019). "This specificity of venetoclax has been shown both in vitro and in vivo to result in a highly potent anti-tumor effect in BCL-2 dependent malignancies, while also sparing platelets." (PMID 30972300, 2019). "The western blot assay and immunohistochemistry studies showed that the expression of Caspase-3, Caspase-8, and Bax in tumor tissues were significantly increased in a dose-dependent manner, while the expression of Bcl-2 was undetectable." (PMID 30651572, 2019). "The anti-tumor roles of fenofibrate on Hep3B cells by inducing apoptosis and necroptosis were dependent on the expression of Bcl-2/caspase family members and RIP1/RIP3 proteins, respectively." (PMID 30824767, 2019). "Consistently, a significant reduction in the expression level of Bcl-2 was observed in nCUR/nSN38-treated CAC tumor tissues." (PMID 31695780, 2019). "Western blot data showed that the protein levels of PCNA, CDK4, CDK6, Cyclin D1, MMP-2, MMP-9, and Bcl-2 were decreased, but cleaved caspase-3 was increased in tumor tissues of ApoE KO mice compared to those of WT mice." (PMID 31275318, 2019). "Most importantly, combination therapy with XPO1 and BCL2 inhibitors blocks tumor progression and metastasis and extends survival in a mouse model bearing patient-derived DHL tumors." (PMID 31752970, 2019). "WapMyc tumor cells express high levels of Bcl-2, Bcl-XL and Mcl-1, and are sensitive to ABT-737 ex vivo." (PMID 30728358, 2019). "The authors used two siRNA to provide a combinatorial anti-cancer treatment using BCL-2 siRNA, which interfere with tumor cell proliferation, and siRNA PKC-ι for inhibition of tumor cell migration." (PMID 31888119, 2019).